TCF4 (transcription factor 4)
Diseases named in the same sentence as TCF4 in open-access papers (continued):
Sharing a sentence is not in itself a finding about the gene and the disease.
neuroblastoma (11 papers, 2011 to 2025). Neuroblastoma (NB) is the most common solid, extracranial childhood tumor. "TCF4-regulated genes identified in a human neuroblastoma cell line associated TCF4 with processes including cell survival, epithelial-to-mesenchymal transition, and neuronal differentiation." (PMID 38470486, 2024). "The TCF4 gene set was created on the basis of the differential expression of genes in neuroblastoma cells after knockdown of TCF4." (PMID 31078131, 2019). "In this study we used genome-wide expression profiling to determine the effects of acute TCF4 knockdown on gene expression in SH-SY5Y neuroblastoma cells." (PMID 24058414, 2013). "To validate the specificity of the TCF4 antibodies, we implemented a RNAi based approach in Neuro2A mouse neuroblastoma cells." (PMID 21789225, 2011). "TCF4 and TCF2 are selective dependency genes for neuroblastoma according to CRISPR KO screens (depmap.org), indicating they are necessary for survival and may explain their conservation between various neuroblastoma lines." (PMID 36147741, 2022). "In addition, deregulated genes upon PHF6 KO significantly overlapped with deregulated genes after Kdm5c KO and with deregulated genes after TCF4 dosage alterations in neuroblastoma cells but not in human blood after correction for multiple testing." (PMID 33149206, 2020).
endometrial carcinoma (10 papers, 2010 to 2026). A malignant tumor arising from the epithelium that lines the cavity of the uterine body. "Overexpression of SOX4 in endometrial carcinomas cell lines caused enhancement of beta-catenin/TCF4-driven transcription, whereas cells stably overexpressing SOX4 demonstrated a low proliferation rate, through transactivation of the p21 gene." (PMID 25366337, 2014). "Makoto and colleagues have shown that SOX-4 has a positive impact on the β-catenin signal transduction through changes in TCF4 expression during the morular differentiation of endometrial carcinoma cells, thus providing the proliferation arrest." (PMID 34157052, 2021). "A positive feedback loop exists to regulate TCF4 expression mediated by β-catenin/p300 in the endometrial carcinoma (Em Ca) cells." (PMID 25499975, 2014). "We firstly examined the localization of Sox7, β-catenin and TCF4 in endometrial cancer cells, HEC-1A." (PMID 23295859, 2012). "Others have reported that expression of β-catenin in endometrial cancer cells upregulates the expression of TCF-4 and that Axin faciltates the degradation of β-catenin." (PMID 20122174, 2010). "Similarly, both GFP/mutant β-catenin S37A and Flag/TCF4 were also localized in the nucleus, indicating that all of these factors were co-localized in the nucleus of endometrial cancer cells." (PMID 23295859, 2012). "Regarding endometrial carcinoma, a recent study demonstrated that LINC00958 played an oncogenic role in EC cell proliferation and metastasis by regulating the miR-145-3p/TCF4 axis." (PMID 35676262, 2022). "Endometrial cancer may also be triggered through the transcriptional regulation of CCND1, the target gene of the β-catenin/Tcf-4 complex, through H3K36 methylation and activation of the WNT signaling pathway." (PMID 30057548, 2018).
epilepsy (10 papers, 2015 to 2025). A brain disorder characterized by episodes of abnormally increased neuronal discharge resulting in transient episodes of sensory or motor neurological dysfunction, or psychic dysfunction. "This indicates that the prevalence of epilepsy and breathing anomalies was distributed equally over the groups with a TCF4 deletion, TCF4 mutation and NRXN1 mutation." (PMID 27072915, 2016).
osteosarcoma (9 papers, 2013 to 2025). A usually aggressive malignant bone-forming mesenchymal neoplasm, predominantly affecting adolescents and young adults. "CT45A1 interacts with the TCF4/β‐catenin complex to promote the metastasis of osteosarcoma cell lines." (PMID 39322998, 2025). "Transcription factor 4, as a key transcription factor in the Wnt/β-catenin pathway, promotes the proliferation of osteosarcoma." (PMID 35342417, 2022). "Dickkopf (Dkk)-3, a member of the Dkk family of Wnt antagonists, can reduce the cytoplasmic accumulation of β-catenin in Saos-2 osteosarcoma cells and inhibit TCF-4 activity in PC12 rat pheochromocytoma cells." (PMID 36535930, 2022). "TWIST1 and TCF4 protein interaction was also validated in osteosarcoma cells." (PMID 33917757, 2021). "Studies have shown that in osteosarcomas, FoxM1 and β-catenin directly bind to the cytoplasm and nucleus, enhancing the nuclear transcription of β-catenin, promoting its binding with TCF4 on the Wnt target gene promoter, enhancing the activity of the Wnt pathway." (PMID 32035486, 2020). "The Twist1 and Wnt/β-catenin signaling pathways play important roles in the development of osteosarcoma, in which Twist1 promotes the expression of specific cell surface receptors in osteosarcoma cells via activating Tcf4-mediated Wnt/β-catenin signaling pathway." (PMID 32974352, 2020).
non-small cell lung carcinoma (8 papers, 2016 to 2024). A group of at least three distinct histological types of lung cancer, including non-small cell squamous cell carcinoma, adenocarcinoma, and large cell carcinoma. "In non-small cell lung cancer, FOXP3 activated the downstream Wnt pathway through the interaction of β-catenin and TCF4, promoting tumor proliferation and metastasis." (PMID 39668835, 2024). "In non-small cell lung cancer (NSCLC), Wnt ligands (Wnt1, Wnt2, Wnt3, and Wnt5a) and other signaling modules (FZD8, PORCN, and TCF-4) are overexpressed." (PMID 37190019, 2023). "Although high levels of TCF4 mRNA expression were detected in NSCLC (non-small cell lung cancer) tissue samples, no detectable expression of TCF-4 mRNA was reported in normal lung tissue." (PMID 32265994, 2020). "In non-small cell lung cancer, DEPDC1B could enhance cell migration and invasion through the activation of Wnt/β-catenin signaling, and this biological effect could be inhibited by the depletion of LEF1 or TCF4." (PMID 35095994, 2021).
Anxiety (7 papers, 2018 to 2025). Intense feelings of nervousness, tension, or panic often arise in response to interpersonal stresses. "Here, authors show that glutamatergic FKBP51 specifically in females mediates adaptive stress effects on anxiety and cognition via TCF4." (PMID 40087272, 2025). "In the elevated plus maze task, we found that Tcf4STOP/+::Neurod6-Cre and control mice exhibited increased closed arm activity compared to Tcf4STOP/+ mice, showing that reinstating Tcf4 in glutamatergic neurons restored the low-anxiety phenotype." (PMID 35535852, 2022). "In contrast, Tcf4STOP/+::Gad2-Cre and Tcf4STOP/+ mice exhibited reduced closed arm activity compared to controls, indicating persistence of the reduced anxiety-like phenotype despite reinstatement of Tcf4 in GABAergic neurons." (PMID 35535852, 2022). "Interestingly, in line with what we found for Fkbp5lox/lox mice that were exposed to ELS, we found that mice that had an OE of Tcf4 in the glutamatergic neurons of the hippocampus showed reduced anxiety-like behaviour." (PMID 40087272, 2025). "Indeed, a follow-up study showed that enhanced TCF4 activity in glutamatergic neurons of the hippocampus, on its own, is sufficient to induce highly similar beneficial effects on anxiety and spatial memory in females in a stressful context as was observed with ELS exposure." (PMID 40087272, 2025). "Given that memory, anxiety-like behavior, and innate behavior were fully rescued when Tcf4 was re-activated only from excitatory neurons, it is reasonable to argue that these phenotypes might mainly depend on having normal TCF4 levels in excitatory neurons." (PMID 35535852, 2022). "Here, we performed proof-of-concept viral gene therapy experiments using a conditional Tcf4 mouse model of PTHS and found that postnatally reinstating Tcf4 expression in neurons improved anxiety-like behavior, activity levels, innate behaviors, and memory." (PMID 35535852, 2022). "TCF4 is a phenotype seed gene for DD, ID, ASD, speech delay, GI problems, dental, Pes planus, hypotonia, and facial dysmorphisms; NFIA is a phenotype seed gene for anxiety, GI problems, and hypotonia; and RGMB appears as a phenotype seed gene for ASD." (PMID 33282601, 2020). "These groups also spent more time in the bright center of the test arena, suggesting less anxiety, while Tcf4 overexpression did not affect either parameter." (PMID 33519394, 2020). "In this proof-of-concept study, genetic reinstatement of Tcf4 in a subset of neurons during early postnatal development corrected multiple behavioral phenotypes in PTHS model mice, including hyperactivity, reduced anxiety-like behavior, memory deficit, and abnormal innate behavior." (PMID 35535852, 2022).
breast tumors (7 papers, 2012 to 2020). "Similar attitude on miR155 function was approved by another group, they proved that miR155 prevented EMT by decreasing TCF-4 expression level in 4T1 breast tumor cells." (PMID 23284982, 2012). "A similar result has been reported in another study with 4T1 breast tumour cells, in which miR155 was found to directly suppress the expression of TCF4 and negatively regulate EMT." (PMID 23284982, 2012). "Analysis of TCGA data confirmed that rs1788027 is an eQTL for TCF4 in breast tumors." (PMID 29666142, 2018). "Thus, it would be of great interest and importance to investigate whether TBLR1 upregulates C-erbB-2 expression via β-catenin/TCF4 transcription complex or others, and whether knocking down of TBLR1 could reduce the tumorigencity of C-erbB-2-overexpressing breast tumors." (PMID 25341494, 2014).
corneal dystrophy (7 papers, 2014 to 2025). The term corneal dystrophy embraces a heterogeneous group of bilateral genetically determined non-inflammatory corneal diseases that are usually restricted to the cornea. "Our data are in accord with previous studies showing that the presence of a TCF4 risk allele at rs613872 is much more common in Caucasian patients with FECD and strongly predisposes to the development of the corneal dystrophy." (PMID 26451375, 2015). "Although this work supplements molecular diagnostics for FECD towards the implementation of precision-medicine approaches in corneal dystrophies, our findings need international standardization of TCF4 expansion testing and the establishment of reliable reference materials." (PMID 41373515, 2025). "However, TCF4 rs613872 and rs17595731 has been investigated in a total of 91 FCD patients, 42 patients with non-Fuchs' corneal dystrophies, and 612 controls of Chinese origin, but they were found to be non-polymorphic." (PMID 25299301, 2014).
diabetes (7 papers, 2009 to 2023). "MYH9, ERBB2, TCF4, VIM (vimentin), LRRK2 and CAV1 have been implicated as a principal mediator of diabetes mellitus." (PMID 36837510, 2023). "Transcription factor 7-like 2 (TCF7L2), which previously known as TCF-4, is a major form of transcription factor involved in the downstream WNT signaling and exhibits the strongest association to diabetes susceptibility." (PMID 31312258, 2019). "Wnt/beta-catenin may represent a link between diabetes and cancer, due to the strong genetic association between specific polymorphisms in the TCF7L2 (TCF4) gene and diabetes." (PMID 28298922, 2017). "The aim of this study was to investigate the effects of ileal interposition (IT) on glucose and insulin resistance (IR) in type 2 diabetic mellitus (T2DM), and the role of T-cell factor 7-like 2 (TCF7L2), formerly known as TCF4, in the downregulation of hyperglycemia following IT." (PMID 23737909, 2013).
medulloblastoma (7 papers, 2011 to 2024). A malignant, invasive embryonal neoplasm arising from the cerebellum. "TCF4 is a transcription factor involved in neurological development and is mutated in 2% of medulloblastomas." (PMID 33172502, 2020). "Whether TCF4 mutations play any functional role in medulloblastoma remains a topic for further investigation." (PMID 33172502, 2020). "TCF4 mutations were a frequent event in our adult Group 4 medulloblastomas." (PMID 33172502, 2020). "Experimental findings highlighted the loss-of-function behind these TCF4 mutations, as exemplified by the fact that mutant TCF4 proteins failed to inhibit the proliferation of medulloblastoma cells, unlike the wild-type TCF4 protein." (PMID 36084949, 2022). "The specific bi-modal distribution of OTX2 binding around the TSSs, as we investigated in medulloblastoma, strongly differs from the binding patterns of MYC and other transcription factors like GATA1 and TCF4." (PMID 22016811, 2011).
ovarian carcinoma (7 papers, 2015 to 2021). A malignant neoplasm originating from the surface ovarian epithelium. "Of note, the study of cisplatin response in ovarian cancer identified loss of chromosome 18q, including TCF4, as being associated with resistance." (PMID 29666142, 2018). "To explore the underlying mechanism of calcitriol regulation of MYC in ovarian cancer cells, we studied the interaction of CCAT2 and TCF4 at the MYC promoter." (PMID 32230936, 2020). "As shown in the model, calcitriol suppresses ovarian cancer cell growth, migration and invasion by down-regulating CCAT2 and repressing its interaction with TCF4, decreasing CCAT2/TCF4 binding to the MYC promoter." (PMID 32230936, 2020).
Rett syndrome (7 papers, 2013 to 2023). A severe neurodevelopmental disorder affecting the central nervous system. "Patients with TCF4 mutations present with phenotype overlap with Rett syndromes and are often diagnosed as RTT-L." (PMID 37408271, 2023). "De novo partial deletions, translocations, missense, and truncating mutations in TCF4 have also been identified in MMID patients without the typical characteristics of PTHS and one missense mutation in TCF4 has been linked to a Rett-like syndrome (RTT-like)." (PMID 34748727, 2021).
intestinal tumor (6 papers, 2011 to 2022). "JUN autoregulates its own transcription via enhancer elements in its promoter and forms a complex with β-catenin and TCF4 to activate JUN transcription in a JNK-dependent manner during mouse intestinal tumor formation." (PMID 26134322, 2015). "We observed increased accumulation of the transcription factor TCF4 and its co-activator β-catenin as well as their downstream oncogenic target protein cyclin-D1 in 56Fe ion-induced intestinal tumors." (PMID 26500891, 2015). "Higher levels were also observed for TCF4 in 56Fe-irradiated intestinal tumors relative to controls." (PMID 26500891, 2015).
psychosis (6 papers, 2013 to 2025). "Recently, Wirgenes and colleagues found that psychosis was associated with elevated TCF4 transcript levels and that TCF4 risk variants were associated with a range of clinical, cognitive and brain morphological abnormalities." (PMID 24058414, 2013). "The TCF4 mRNA expression level in blood was significantly increased in psychosis patients compared with controls and positively correlated with positive- and negative-symptom levels." (PMID 41226544, 2025). "In the MTAG results, a total of 146 genes were observed for three or more disorders, including some genes that were previously known to be involved in psychosis, such as DRD2 and TCF4, which were originally reported in SCZ and DEP, while our data indicated their association with BD." (PMID 32606422, 2020).
colitis (5 papers, 2018 to 2023). Inflammation of the colon. "We established Tcf4 haplodeficiency in Was-deficient animals that are prone to systemic autoimmunity and that develop severe colitis with 100% penetrance." (PMID 30410494, 2018). "We crossed the DC-specific Tcf4 conditional knockout (CKO) strain with Il10-deficient mice (Il10−/−) that develop colitis resembling human IBD." (PMID 30410494, 2018). "While Tcf4 haplodeficiency in Was-deficient mice specifically reduced pDC numbers it did not affect the heightened activation of immune responses or the development of colitis." (PMID 30410494, 2018). "Because Tcf4 haplodeficiency results in only a partial impairment of pDCs, we sought to examine the effect of a more profound pDC depletion on colitis." (PMID 30410494, 2018). "Moreover, treatment with bicuculline (Bic, a GABAAR inhibitor) increased the levels of PCNA, β−catenin, and TCF4 in mice with colitis." (PMID 36232509, 2022). "Therefore, nuclear YAP participated in the β-catenin/TCF4 transcriptional complex in colon cells and the activity of this complex was normal during homeostasis but was dramatically enhanced during colitis-induced regeneration and carcinoma." (PMID 29396428, 2018). "Monoallelic Tcf4 deletion, which was previously shown to abrogate experimental lupus, did not affect autoimmunity manifestations or colitis in WASP-deficient animals." (PMID 30410494, 2018). "Our results demonstrating no impact of Tcf4 specific targeting on the occurrence and the severity of colitis in Was-deficient animals argue against an important role of pDCs in this process." (PMID 30410494, 2018). "We showed that inhibition of GABAAR significantly increased the expression levels of β−catenin, TCF4, and PCNA, suggesting that inhibition of GABAAR may exert protective effects against colitis through the Wnt signaling pathway." (PMID 36232509, 2022).
Fuchs' endothelial dystrophy (5 papers, 2014 to 2020). Fuchs endothelial corneal dystrophy (FECD) is the most frequent form of posterior corneal dystrophy and is characterized by excrescences on a thickened Descemet membrane (corneal guttae), generalized corneal edema, with gradually decreased visual acuity. "Another gene from our 1-HLOD support interval, TCF4, has repeatedly been association with Fuchs endothelial dystrophy, which is characterized by the deterioration of the corneal epithelium." (PMID 31367973, 2019). "Multiple genetic loci have been linked to Fuchs' endothelial dystrophy, including but not limited to TCF4, COL8A2, SLC4A11, ZEB1 and LOXHD1." (PMID 29685994, 2018). "A meta-analysis of TCF4 and PTPRG gene variants in Fuchs' corneal dystrophy (FCD)." (PMID 25299301, 2014).
mental disorder (5 papers, 2015 to 2025). A disease that has its basis in the disruption of mental process. "The TCF4 gene is associated with many mental disorders and deficiencies, and this gene is suggested as a gene candidate of high risk for SCZ." (PMID 41226544, 2025). "The interaction between Tcf4 and Math1 regulates neuronal progenitor differentiation and is associated with the pathogenesis of mental disorders." (PMID 35406121, 2022). "The list of pleiotropic risk factors acting across a variety of psychiatric disorders includes such well-described candidates as NEGR1, SOX5, SORCS3, DCC, and TCF4 and indicates that MDD and PTSD are part of the greater spectrum of mental disorders with shared genetic liability." (PMID 33905376, 2022).